DDX42 (DEAD-box helicase 42)
Description:
ATP-dependent RNA helicase that binds to partially double-stranded RNAs (dsRNAs) in order to unwind RNA secondary structures. Unwinding is promoted in the presence of single-strand binding proteins. Also mediates RNA duplex formation thereby displacing the single-strand RNA binding protein. ATP and ADP modulate its activity: ATP binding and hydrolysis by DDX42 triggers RNA strand separation, whereas the ADP-bound form of the protein triggers annealing of complementary RNA strands. Required for assembly of the 17S U2 SnRNP complex of the spliceosome, a large ribonucleoprotein complex that removes introns from transcribed pre-mRNAs: DDX42 associates transiently with the SF3B subcomplex of the 17S U2 SnRNP complex and is released after fulfilling its role in the assembly of 17S U2 SnRNP. Involved in the survival of cells by interacting with TP53BP2 and thereby counteracting the apoptosis-stimulating activity of TP53BP2. Relocalizes TP53BP2 to the cytoplasm.
Synonyms: RHELP; RNAHP; SF3b125; SF3B8; DDX42P
Tractability: Small molecule: a structure with a bound ligand is known. PROTAC: UniProt records ubiquitination sites on it; ubiquitination databases record sites on it; its protein half-life has been measured; a small molecule that binds it is known.
Target class: Enzyme; Hydrolase
Gene: Protein-coding gene on chromosome 17 (63,773,603 to 63,819,429, forward strand). Ensembl gene ENSG00000198231.
Subcellular location: Cytoplasm; Nucleus; Nucleus, Cajal body (Isoform 2); Nucleus speckle
Subcellular location (Human Protein Atlas): Nuclear speckles
Pathways (Reactome):
Metabolism of RNA: mRNA Polyadenylation; mRNA Splicing - Major Pathway; mRNA Splicing - Minor Pathway
Chromatin organization: CHD1 and CHD2 subfamily
Disease: Dengue Virus-Host Interactions
Gene Ontology:
Molecular function: ATP hydrolysis activity; protein binding; RNA binding; RNA helicase activity; ATP binding; nucleic acid binding
Biological process: intracellular protein localization; regulation of apoptotic process; U2-type prespliceosome assembly
Cellular component: cytoplasm; membrane; nuclear speck; nucleus; U2-type prespliceosome; nucleoplasm; Cajal body
Genetic constraint (gnomAD): Loss-of-function variants: 21 observed, 101.97 expected, observed/expected ratio (o/e) 0.21, 90% interval 0.14 to 0.3. The upper end of that interval is the gene's LOEUF score, 0.3, which puts it in group 1 of 6, group 1 being the genes least tolerant of losing a copy. Missense variants: 848 observed, 1,255.5 expected, observed/expected ratio (o/e) 0.68, 90% interval 0.64 to 0.71. Synonymous variants: 399 observed, 420.17 expected, observed/expected ratio (o/e) 0.95, 90% interval 0.87 to 1.03.
Homologues: Orthologues: chimpanzee DDX42 (99% identical), macaque DDX42 (99% identical), dog DDX42 (96% identical), rabbit DDX42 (96% identical), mouse Ddx42 (96% identical), pig DDX42 (95% identical), guinea pig DDX42 (95% identical), rat Ddx42 (95% identical), tropical clawed frog ddx42 (77% identical), zebrafish ddx42 (72% identical), Drosophila melanogaster CG6418 (45% identical), Caenorhabditis elegans C46F11.4 (40% identical). Paralogues in human: DDX17 (25% identical), DDX5 (24% identical), DDX46 (23% identical), DDX3Y (22% identical), DDX3X (21% identical), DDX4 (20% identical), DDX43 (20% identical), DDX41 (20% identical), DDX53 (19% identical), DDX23 (19% identical), DDX54 (18% identical), DDX59 (18% identical), and 26 more.
Diseases named in the same sentence as DDX42 in open-access papers:
DDX42 is named in the same sentence as 12 diseases in open-access papers, as found by Europe PMC text mining. Sharing a sentence is not in itself a finding about the gene and the disease. The quoted sentences say what the papers report.
hepatocellular carcinoma (2 papers, 2025). A malignant tumor that arises from hepatocytes. "In contrast, overexpression of DDX42 in hepatocellular carcinoma activates the PI3K/AKT signaling pathway, enhancing proliferation, radioresistance, and sorafenib resistance, suggesting context-dependent oncogenic activity." (PMID 41463182, 2025).
Anxiety (1 paper, 2025). Intense feelings of nervousness, tension, or panic often arise in response to interpersonal stresses. "In PAH rats, anxiety- and depression-like behaviors were observed, and qPCR confirmed altered expression of CHD8, DDX42, and EIF3D consistent with in-silico findings." (PMID 41280439, 2025).
colorectal cancer (1 paper, 2024). A primary or metastatic malignant neoplasm that affects the colon or rectum. "ATP-dependent RNA helicase DDX42 protein is predicted to be an RBP and has shown experimental evidence in colorectal cancer progression." (PMID 38866007, 2024).
depression (1 paper, 2025). "Candidate biomarkers including CHD8, DDX42, and EIF3D should be assessed in larger, independent cohorts of patients with PAH, with and without depression, as well as in MDD cohorts, to determine their diagnostic or prognostic potential." (PMID 41280439, 2025).
leukemia (1 paper, 2023). A malignant (clonal) hematologic disorder, involving hematopoietic stem cells and characterized by the presence of primitive or atypical myeloid or lymphoid cells in the bone marrow and the blood. "Ddx42 is a member of the DEAD/H-box helicase family that is broadly classified as oncogenes in various cancers, including leukemia." (PMID 37958330, 2023).
sarcopenia (1 paper, 2025). Progressive decline in muscle mass due to aging which results in decreased functional capacity of muscles. "MMP24‐AS1, HLA‐DRB6, HLA‐DQA2, DDX42, BAG6, NUSAP1, LINC00940, NME1‐NME2 and AS3MT in the amygdala region showed detrimental effect on all the five sarcopenia‐related traits, whereas HLA‐DRB1, HLA‐DQB1‐AS1 and C6ORF3 showed protective effect (p < 0.05)." (PMID 39535371, 2025). "The over‐expression of nine genes (MMP24‐AS1, HLA‐DRB6, HLA‐DQA2, DDX42, BAG6, NUSAP1, LINC00940, NME1‐NME2 and AS3MT) in the amygdala region showing detrimental effect on all the five sarcopenia‐related traits, whereas three genes (HLA‐DRB1, HLA‐DQB1‐AS1 and C6ORF3) showing protective effect." (PMID 39535371, 2025).
cancer (5 papers, 2019 to 2025). A tumor composed of atypical neoplastic, often pleomorphic cells that invade other tissues. "Cancer-driving mutations of SF3B1 target the residues in the RNA path that directly interact with DDX42 and DDX46." (PMID 36797247, 2023). "Intriguingly, the SF3B1 residues that interact with DDX42 only are spared by cancer-derived mutations." (PMID 36797247, 2023). "In addition, seven SF3B1 residues that interact with both DDX46 and DDX42 are targeted for mutations in cancer, including the most frequently mutated residue Lys700." (PMID 36797247, 2023). "In contrast to DDX42, three SF3B1 residues (Asp894, Tyr898 and Glu902) that interact with DDX46 only are mutated in cancer." (PMID 36797247, 2023). "Together with structure-guided biochemical analysis, our study reveals a coherent picture on the roles of DDX42 and DDX46 in U2 snRNP assembly and provide insights into SF3B1 cancer mutations." (PMID 36797247, 2023). "This analysis identifies important roles of DDX42 N-plug and DDX46 acidic loop in mediating the effects of cancer mutations in SF3B1." (PMID 36797247, 2023). "While DDX46 functions as an RNA splicing factor similar to DDX42, detailed reports on the biological functions of SMNDC1 and UNK in cancer are currently limited." (PMID 40831000, 2025). "Remarkably, all seven residues are located in the RNA path and directly recognize the N-plug of DDX42 and the acidic loop of DDX46; substitutions of these residues in cancers impair the binding of both DDX4246 and DDX4623." (PMID 36797247, 2023). "Our study suggests distinct mechanisms of DDX42 and DDX46 in cancer development." (PMID 36797247, 2023).
tumor (3 papers, 2024 to 2025). "In this research, DDX42 was found to be highly associated with tumour progression, acquired radio‐resistance and sorafenib resistance in HCC." (PMID 40831000, 2025). "Since abnormal splicing regulation has been closely linked to tumor cell proliferation and invasiveness, one might argue that DDX42 downregulation could endow RAS-mut NIFTPs with enhanced proliferative capacities and a tendency for more rapid growth." (PMID 39684824, 2024). "DDX42 was highly expressed in HCC than in para‐tumour tissues and was a prognostic factor for HCC patients." (PMID 40831000, 2025). "IHC staining of DDX42 was performed on 10 paired HCC specimens, and the expression of DDX42 was higher in the HCC section than in the para‐tumour section." (PMID 40831000, 2025). "At present, there were no reports about the association between GRB2 and DDX42 regarding regulating tumour progression and treatment resistance." (PMID 40831000, 2025). "Additionally, we demonstrated that the expression differences between tumour and normal tissues of DDX42 and GRB2 in HCC specimens via IHC experiments." (PMID 40831000, 2025). "Therefore, systematic transcriptome analysis might be leveraged in further research to analyse the target genes of DDX42 in tumour progression." (PMID 40831000, 2025). "From these RBPs, only HNRNPH1 is differentially expressed between tumor core and peripheral neoplastic cells, while four RBPs (HNRNPH1, HNRNPF, TRA2A, DDX42) are reported to be differentially spliced themselves." (PMID 39936571, 2025). "In conclusion, our findings facilitate the acknowledgment of tumour initiation and mechanisms of treatment resistance in HCC, and targeting the axis of DDX42 and GRB2 may be promising strategies for synergy with radiotherapy or sorafenib for HCC patients." (PMID 40831000, 2025). "However, based on bioinformatics analysis, we first supposed that DDX42 might be involved in the cell proliferation and treatment resistance phenotypes by urging the maturation process of GRB2, which has been fully understood in several tumour types." (PMID 40831000, 2025).
blood cancers (1 paper, 2023). "Although somatic mutations in human DDX42 are infrequent, overexpression and copy number gain of this gene have been reported in blood cancers, supporting its oncogenic roles." (PMID 37958330, 2023).
DDX42 also shares sentences with these, for which no sentence is quoted: Flavivirus Infections (1 paper); follicular adenomas (1); papillary thyroid carcinomas (1).